INSR (insulin receptor)
Diseases named in the same sentence as INSR in open-access papers (continued):
Sharing a sentence is not in itself a finding about the gene and the disease.
Hyperglycemia (continued). "Blockade of pancreatic trypsin in the old by a two-week oral treatment with a serine protease inhibitor (tranexamic acid) serves to significantly reduce trypsin accumulation in organs outside the intestine, collagen damage, as well as hyperglycemia and insulin receptor cleavage." (PMID 39418235, 2024). "Decreased INSR expression may lead to an increase in insulin production as a compensatory response to hyperglycemia." (PMID 39337631, 2024). "When IR occurs in the liver, the tyrosine phosphorylation of IRS1 is severely damaged by hyperglycemia, leading to a decrease in the liver’s ability to absorb glucose, affecting proximal defects in the INSR, IRS1, PI3K, and AKT pathways and impairing the insulin transduction pathway." (PMID 39272556, 2024). "The hyperglycemia that results from simultaneous inhibition of InsR signaling could be overcome through the design of more selective inhibition strategies, for instance inhibitors that target IGF-1R over InsR (perhaps through allosteric mechanisms)." (PMID 37858153, 2023). "Type B insulin resistance, a very rare condition due to insulin receptor antibodies (IR-A), usually presents with hyperglycaemia but may also uncommonly present with fasting or postprandial hypoglycaemia and similar biochemical pictures to insulinoma." (PMID 37892096, 2023). "These include decreased insulin receptor phosphorylation rendering them inactive, with subsequent development of fatty liver, increased hepatic TG content, an impaired plasma lipid profile, hyperglycemia, hyperinsulinemia, as well as impaired glucose and insulin tolerance test scores." (PMID 35055468, 2022). "We suggest that these mice have reduced insulin sensitivity (hyperglycemia) and as a compensatory mechanism there is overactivation/expression of insulin receptor in the brain rendering neuronal circuits resistant to seizure induction after injection of insulin." (PMID 35264925, 2022). "Improvement in insulin receptor signaling and reduction of hyperglycemia and lipid deposits in the liver of diabetic rats has been reported, as well as antidiabetic and antioxidant effects, which directly supports the notion of the antidiabetic activity of morin." (PMID 35434481, 2022). "In response to hyperglycaemia, insulin is released into the blood circulation by pancreatic β cells, and its anabolic effect on target tissues is influenced by its transmembrane receptor, insulin receptor (IR)." (PMID 35806275, 2022). "The same group of investigators also reported that daily taVNS applications for 34 consecutive days prevented development of hyperglycemia in Zucker diabetic fatty rats and increased insulin receptor expression in various tissues, including liver and skeletal muscle." (PMID 35441808, 2022). "Partial deletion of the insulin receptor is also associated with significant hyperglycemia and hyperinsulinemia, despite exhibiting no changes in insulin signaling." (PMID 34568323, 2021). "Dysregulation of glucose homeostasis would be a major concern for using BMS-754807 in the clinic, as inhibition of the insulin receptor could lead to hyperglycemia." (PMID 34831014, 2021). "Several phase III clinical trials targeting IGF-1R with small molecule inhibitors have so far failed due to side effects such as hyperglycemia and metabolic syndrome caused by the homology of IGF-1R and insulin receptor (IR) and IGF elevation in response to disruption of glucose homeostasis." (PMID 32355893, 2019). "We presumed here that hyperglycemia might abate InsR and IGF-1R expressions in the myenteric ChAT+ neurones but the detailed mechanism needs to be further clarified." (PMID 28931726, 2017). "Liver is a relevant organ to assess the impact of insulin and glucagon deficiency because re-expression of the glucagon receptor in the liver of STZ-treated Gcgr-/- mice, and conditional inactivation of the insulin receptor in hepatocytes are both sufficient to trigger hyperglycemia." (PMID 27092792, 2016).
Hyperglycemia (continued). "However, inhibition of IGF-1R directly is not applicable for prevention because of the potential side effects of small-molecule IGF-1R inhibitors, such as hyperglycemia due to cross-reactivity to the insulin receptor (IR)." (PMID 27708216, 2016). "By targeting the insulin receptor kinase directly and thereby activating the full range of downstream pathways radiating from the insulin receptor, the peptide may prove to be an alternative or addition to other drugs currently used for reducing hyperglycemia." (PMID 27294151, 2016). "HbA1c reflects the average blood glucose level in the past 8-12 weeks, and it is therefore inferred that ketosis may occur in the context of chronic hyperglycemia, leading to metabolic decompensation through glucotoxic mechanisms that impair β-cell reserves and insulin receptor function." (PMID 38027130, 2023). "However, the aggregate data suggest that insulin receptor activation may be a more important factor than hyperglycaemia in determining tumour growth." (PMID 35256755, 2022). "In a murine model, deletion of insulin receptor (IR) in proximal tubules has elevated hyperglycemia, conceivably because of increased regional renal gluconeogenesis, where glucose could be derived from non-carbohydrate sources, e.g., renal tubular lipids or triglycerides." (PMID 34268323, 2021). "In addition, we suggest that insulin-related molecules partly mimicking insulin may block the insulin receptor, and thereby contribute to hyperglycaemia." (PMID 34170845, 2021). "In T2D, INSR becomes resistant to insulin cues for the activation of downstream signaling which controls hepatic glucose production (gluconeogenesis) and blood glucose clearance (primarily into skeletal muscle); this results in hyperglycemia and glucose intolerance." (PMID 31378829, 2020). "In addition, considering that some of the EGFR inhibitors induced hyperglycemia in the clinic, which was possibly through inhibition of the INSR and IGF1R kinases, we also tested this drug in parallel with AZD9291 in the INSR and IGF1R transformed isogenic BaF3 cells." (PMID 28407693, 2017). "We previously demonstrated that podocytes are insulin-responsive cells in vitro, and the specific deletion of the podocyte insulin receptor (IR) in vivo disrupts glomerular function, causing features reminiscent of diabetic nephropathy, independent of hyperglycaemia." (PMID 28852804, 2017). "Moreover, Aloe vera leaves extract has also demonstrated hypoglycemic effect in both T1DM and T2DM rats, and the quercetin-rich onion peel extract had shown to improve hyperglycaemia and insulin sensitivity by upregulation of insulin receptor and glucose transporter 4 mRNA expressions." (PMID 25883984, 2015). "Therefore, it appears that an insulin deficiency rather than hyperglycemia induces aberrant neuronal insulin receptor signaling and contributes to sensory nerve dysfunction in type 1 diabetic neuropathy." (PMID 24023699, 2013). "In whole-body NEU3-overexpressing transgenic mice, insulin signaling is attenuated, with reduced phosphorylation of the insulin receptor and downstream targets such as IRS-1 and Akt, leading to glucose intolerance and fasting hyperglycemia." (PMID 41301440, 2025). "Interestingly, but not surprisingly, autosomal dominant -negative mutations of INSR are not found in populations with high consanguinity rate but can be identified in probands lacking parental history of hyperglycemia (our two cases) on the basis of extrapancreatic features." (PMID 36178555, 2023). "F1:Fin have a higher accumulation of hepatic glycogen as a result of hyperglycemia, a lower expression of GLUT-2, IR (insulin receptor), and AR in the liver, which are symptoms of liver steatosis as well as higher body weight." (PMID 36359245, 2022).
Hyperglycemia (continued). "The micronutrient profile of dairy could contribute to attenuated hyperglycemia as the cellular influx of calcium plays a pivotal role in nutrient intake and in endothelial‐dependent vasodilation, and magnesium is essential for optimal coupling and signaling through the insulin receptor." (PMID 30510711, 2018). "In support of the role of HMGA1 in INSR gene transcription, in vitro investigations in beta-pancreatic cells demonstrated that sustained hyperglycemia impaired HMGA1 expression, a condition affecting INSR content in beta cells and, thus, insulin secretion." (PMID 30034366, 2018). "The results indicate that the insulin receptor is one of the target pathways affected by miR-15b and miR-16 in REC, and elevated levels of the microRNAs protect REC in hyperglycemia." (PMID 25888955, 2015). "The therapeutic use of anti-IGF-2 neutralizing antibodies may offer better tolerability by avoiding hyperglycemia, a common side effect of small molecule IGF1R inhibitors, due to cross-reaction with the Insulin Receptor." (PMID 36809604, 2023). "The binding of ENPP-1 to the α-domain of the insulin receptor prevents the activation of insulin signaling with subsequent GLUT-4 storage resulting in insulin resistance and hyperglycemia that could result in DM." (PMID 35055468, 2022). "Mice lacking the insulin receptor on alpha cells (αIRKO) exhibit hyperglycemia and hyperglucagonemia, indicating that insulin receptor signalling is required for an appropriate alpha cell secretory response to glucose." (PMID 34659118, 2021). "The observed activities of NPC43 against hyperglycemia and glucose intolerance in Leprdb/db mice may also be attributed to NPC43-mediated activation of INSR/AKT/AS160 signaling in skeletal muscle to promote glucose uptake." (PMID 31378829, 2020). "The IGF-1R antibody therapy resulted in hyperglycemia and metabolic syndrome, and the receptor tyrosine kinase inhibitors manifested metabolic toxicities, most likely due to high similarity between IGF-1R and insulin receptor." (PMID 30185144, 2018). "No patient developed hyperglycemia, suggesting that the insulin receptor is not a clinically significant target of AXL1717 in contradistinction to the IGF-1R inhibitor OSI-906 and the IGF-1R targeting monoclonal antibodies." (PMID 29113409, 2017). "The results revealed that it was much less potent than AZD9291 against both INSR (GI50: 2.8μM versus 0.5 μM) and IGF1R (GI50: 3.6 μM versus 0.56 μM) indicating that there was much less chance that this drug could induce the hyperglycemia adverse effects." (PMID 28407693, 2017). "In addition to its direct interaction with the kinase domain of the insulin receptor, KYCCSRK indirectly mitigates untoward effects of hyperglycemia by regulating cellular levels of the heme oxygenase isozymes, HO-1 and HO-2." (PMID 27294151, 2016). "Pancreatic α-cell targeted disruption of insulin receptor expression in mice results in glucose intolerance and hyperglycemia, not seen in these animals." (PMID 25946091, 2015). "Neither adipose nor muscle insulin receptor knockout mice have pathological changes in glucose and insulin levels, but liver insulin receptor knockout mice develop both hyperglycaemia and hyperinsulinaemia." (PMID 25742416, 2015). "However, the consequent cytoplasmatic hyperglycemia causes an overactive mTOR/S6, leading to a negative feedback loop in the IGFR/InsR intracellular signaling (IR at cellular level)." (PMID 40277891, 2025). "Moreover, IR-induced defects in insulin receptor signaling can provoke diabetic nephropathy-like pathological conditions even in the absence of hyperglycemia." (PMID 40748976, 2025). "The indirect impact on insulin receptor signaling might also play a role, as IGF-1R inhibitors block the insulin receptor, preventing insulin from binding to its receptor, thereby inhibiting cellular glucose uptake and leading to hyperglycemia." (PMID 40496563, 2025).
Hyperglycemia (continued). "Therefore, as expected, hyperglycemia enhances IGF1R/insulin receptor signaling in both non-tumorigenic and malignant breast epithelial cells." (PMID 24260287, 2013). "Moreover, other rat studies have shown that some honey phenols, such as quercetin, could alleviate hyperglycemia by stimulating insulin signaling and GLUT-4 expression through increasing the tyrosine phosphorylation on insulin receptor substrate (IR), and direct activation of the P13k/Akt pathway." (PMID 40901285, 2025). "The action of insulin after binding to the insulin receptor on the cell surface (e.g. glucose uptake in skeletal muscle, inhibition of glycogenolysis and gluconeogenesis) is mediated by the intracellular PI3K pathway, and thus PI3K inhibition may lead to hyperinsulinemic hyperglycemia." (PMID 39437820, 2024). "Studies in animal models have demonstrated that mice lacking the insulin receptor on alpha cells (α IRKO) feature hyperglycemia and hyperglycemia." (PMID 35819935, 2022). "Although most of these antibodies do not bind to the insulin receptor (INSR), some of them partially cross-react with the INSR leading to hyperglycemia in clinical studies." (PMID 24904527, 2014).
breast cancer (135 papers, 2006 to 2026). A primary or metastatic malignant neoplasm involving the breast. "Studies have identified leptin, aromatase, insulin receptor, peroxisome-proliferator-activated receptor gamma (PPARγ), and lifestyle changes as other potential targets for obesity-associated breast cancer treatment." (PMID 37626871, 2023). "A number of studies also linked heparanase activity to the augmented INSR signaling in several types of malignant tumors (i.e., myeloma, breast carcinoma, synovial sarcoma)." (PMID 38078007, 2023). "In breast cancer (except for breast fibroadenoma), the expression level of insulin receptor increases, which is one of the independent risk factors for a worse prognosis for breast cancer patients with type 2 diabetes after insulin treatment." (PMID 34485124, 2021). "In conclusion, p‐IGF‐1R/InsR positivity in ER+ breast cancer is associated with reduced benefit from adjuvant tamoxifen in postmenopausal patients." (PMID 31490549, 2020). "High InsR/IGF-IR ratios are associated with resistance to IGF-IR inhibition in human breast cancer cells." (PMID 32493414, 2020). "The expression patterns of IGF1R, InsR and pIGF1R are therefore important to elucidate in this complex network, its involvement in breast cancer, and its association with prognosis in different treatment groups." (PMID 28030849, 2017). "Indeed, ITGB1 and ITGB3 have been reported to play an important role in HER-2-induced mammary tumor growth and metastasis to the lungs, and this is associated with the promotion of signaling through the insulin receptor-AKT-mTORC1 pathway." (PMID 37175499, 2023). "Moreover, certain cancers, including breast, express high levels of the insulin receptor (IR), and increased circulating insulin is associated with breast cancer recurrence and death." (PMID 25849721, 2015). "In the previous study, we explored the influence of CELF1 on the alternative splicing of INSR and observed a shift in its oncogenic effects in breast cancer; these effects were found to differ among various molecular subtypes." (PMID 41306913, 2025). "A large cohort of 1904 breast cancer patients from the METABRIC study demonstrated that AGER and the insulin receptor are co-expressed and associated with a worse prognosis." (PMID 40647480, 2025). "Our previous study revealed that CELF1 exerts its influence by modulating the LIP/LAP molar ratio, thereby controlling the diverse mRNA splicing profiles of INSR in breast cancer cells and affecting cell aggressiveness." (PMID 41306913, 2025). "In breast cancer tissues, the “A” isoform of the insulin receptor (IR-A) is upregulated and can be activated by insulin or IGF27." (PMID 40764810, 2025). "Remarkably, proteins prominently expressed in NmFMC compared with other groups, such as F13A1, CENPF, INSR, SCAF1 and PDK1, have been implicated in human breast cancer, further supporting the potential use of FMC as a model for studying human breast cancer." (PMID 38951817, 2024). "Leukemia cells THP-1, TK6, and breast cancer cells MCF-7 showed the highest INSR expression, but THP-1, MCF7, and squamous cell carcinoma cell SCC4 showed the highest GLUT4 expression." (PMID 39378614, 2024). "To investigate the potential effects of insulin on ARG treatment, we first determined the expression of insulin receptor on six breast cancer cell lines, three lung cancer cell lines, and three ovarian cancer cell lines." (PMID 38374190, 2024). "In breast cancer epithelial cells, the insulin receptor is overexpressed up to 10 times the normal amount." (PMID 38397072, 2024). "It has been shown that when the abundance of INSR is increased (in breast cancer), there is poor survival for the patients." (PMID 36890818, 2023). "Early studies demonstrated that insulin receptor (IR) was both overexpressed and phosphorylated in breast cancers compared to normal tissue." (PMID 36920947, 2023).